NCR3 (natural cytotoxicity triggering receptor 3)
Diseases named in the same sentence as NCR3 in open-access papers (continued):
Sharing a sentence is not in itself a finding about the gene and the disease.
tumor (316 papers, 2005 to 2025). "Additionally, the activating receptor-associated genes in the tumor-infiltrating NK (TiNK) cells were broadly downregulated, particularly the activating receptor NKp30 (NCR3)." (PMID 41254082, 2025). "In this study, we silenced E6/E7 in Caski and Ms751 cell and the whole-genome microarray analysis showed that many tumor microenvironment associated genes were down-regulated, such as NCR3, a gene associated with immune response, and BIRC3, a gene related to regulation of inflammatory response." (PMID 28303973, 2017). "We also found suggestive evidence for association of top SNPs with the expression of EGFL8, which has previously been implicated in cancer progression, and NCR3, a gene that encodes a natural cytotoxicity receptor that may aid NK cells in lysing tumor cells." (PMID 23326239, 2013). "In GIST, NK cells express decreased levels of their specific activatory receptor NKp30/NCR3 both inside the tumor and at the periphery compared to circulating NKp30+ NK cells of healthy donors, despite the similarity of NK cell blood counts in both groups." (PMID 38136307, 2023). "KIR2DL1/S1+ CD8+ T cells show over-expression of components of the FcεRI and NCR3 signaling pathways, genes which play an important role in tumor killing by T and NK cells." (PMID 33076479, 2020). "The natural cytotoxicity receptor NKp30 (natural cytotoxicity triggering receptor 3, NCR3) has been identified to trigger NK-cell–mediated killing of several tumor cell lines, virus-infected cells, fungal cells, and also dendritic cells." (PMID 29121672, 2017). "This is of special interest for NKp30 and its tumor associated ligand BAT3, since NKp30 (NCR3, CD337) plays a crucial role in target-cell lysis as well as in the cross talk between NK cells and iDCs." (PMID 18852879, 2008). "Analysis of our previously published RNA-Seq dataset, which includes various cell types found in OC ascites and omental metastases, showed selective expression of KIR2DL1, KIR2DL4, and NCR1 in tumor-associated NK cells (TANK), and KLRK1 and NCR3 in both TANK and tumor-associated T cells (TAT)." (PMID 39563446, 2024). "Among others, germline-encoded activating receptors, such as KLRK1 (also known as NKG2D) and the Natural cytotoxicity receptors (NCRs), such as NKp46 (NCR1), NKp44 (NCR2), and NKp30 (NCR3), can synergize to overcome inhibitory thresholds and evoke NK cell anti-tumor functions." (PMID 34539622, 2021). "Gene expression analysis revealed higher levels of activation, cytotoxicity, and memory markers (e.g., CD69, PRF1, TNF, KLRB1, and NCR3) in iMRAS-activated CAR-iNKT cells, correlating with their enhanced tumor-killing potential." (PMID 40297706, 2025). "PGE2 inhibits NK cell effector receptors, such as NCR2/NKp44, NCR1/NKp46, NCR3/NKp30, NKG2D, and CD16, leading to impaired function and promoting tumor immune evasion." (PMID 39609700, 2024). "NKp30 (NCR3/CD337) is a natural cytotoxicity receptor (NCR) that is expressed on NK cells and stimulated by tumor-expressed B7-H6 to elicit a cytolytic effect." (PMID 34064396, 2021). "Activating cytotoxicity receptors (NCRs), NKp46 (NCR1, CD335), NKp44 (NCR2, CD336), NKp30 (NCR3, CD337), contain immunoglobulin-like domains binding to tumor antigens, viral proteins, and some bacterial components." (PMID 34017328, 2021). "Tumor-infiltrating clusters NK1 and NK5 showed high expression of NK-activating receptors, including NKG2D-DAP10 (KLRK1/HCST), NKG2C (KLRC2), CD94 (KLRD1), and NKp30 (NCR3), suggesting that they were robustly activated." (PMID 40315330, 2025). "In contrast, members of the TNF receptor superfamily (TNFSF), which mediate the noncanonical NF-κB pathway, a potential tumor-promoting mechanism (NCR3, CD40LG, LTA, LTB, and TNFRSF13C), were observed in East Asian and Mixed ancestry populations (TCGA)." (PMID 41387728, 2025).
tumor (continued). "Expression of genes coding for NK-cell receptors including NCR3 (NKp30) in the malignant T cells was present in five patients, which can be explained either by enhanced Myc signaling or high IL15 expression in the tumor microenvironment." (PMID 39169943, 2024). "We observed that the expression of genes involved in NK crosstalk with DCs and tumour cells (DNAM1, CRTAM, CD96), promoting NK cell activation (NCR3(NKp30)) or modulating NKT activity (CD1d) was strongly and positively correlated with that of the 5 previously identified markers of good prognosis." (PMID 23758773, 2013). "In tumor-bearing mice, the frequency of CD11b+Gr1+ MDSCs inversely correlates with the expression of NK cell-activating receptors including NKG2D and natural cytotoxicity triggering receptor 3 (NCR3, best known as NKp30) on the NK cell surface, as well as with IFNG and PRF1 production." (PMID 36319998, 2022).
cancer (78 papers, 2011 to 2026). A tumor composed of atypical neoplastic, often pleomorphic cells that invade other tissues. "Studies have shown that in cancers, the levels of activating receptors (NCR1, NCR2, NCR3) are decreased, and this finding has been linked to poor prognosis." (PMID 38628992, 2024). "who observed from circulating leukocytes in healthy and cancer bearing dogs that NCR3, rather than NCR1, was more indicative of the transcriptional signature of canine NK cells." (PMID 40443661, 2025).
infection (23 papers, 2009 to 2023). The state of being infected such as from the introduction of a foreign agent such as serum, vaccine, antigenic substance or organism. "Similar results were obtained, TNF participated in antimicrobial humoral response-related anti-infection pathways, NCR3 was still involved in natural killer cell mediated immunity." (PMID 34311758, 2021). "In the present study a significant increase in NCR3 expression was detected in N'Dama at 14 dpi, when parasites appeared in the bloodstream, relative to pre-infection." (PMID 19409086, 2009). "The natural cytoxicity triggering receptor 3 gene (NCR3) that may contribute to the increased efficiency of activated NK cells to lyse cells in the inflammatory response, showed a significant increase in gene expression in the N'Dama group at 14 dpi (1.6-fold, P = 0.0258) relative to pre-infection." (PMID 19409086, 2009). "A number of additional genes that play important roles in the immune response to infection were also increased in expression in response to trypanosome infection (GZMB, LYZ, CYBB and NCR3)." (PMID 19409086, 2009). "Also, the network revealed the possible mechanisms of TNF and NCR3 in regulating T1DM, by anti-infection pathways and natural killer cell mediated immunity, respectively." (PMID 34311758, 2021).
NCR3 also shares sentences with these, for which no sentence is quoted: cervical cancer (16 papers); leukemia (13); neuroblastoma (10); pancreatic cancer (9); HCMV infection (7); hepatocellular carcinoma (7); HIV-1 infection (6); multiple myeloma (6); chronic lymphocytic leukemia (5); ovarian carcinoma (5); acute promyelocytic leukemia (4); gastrointestinal stromal tumor (4); glioma (4); myeloid leukemia (4); prostate carcinoma (4); acute lymphoblastic leukemia (3); chronic myeloid leukemia (3); Cirrhosis (3); co-infection (3); colon carcinoma (3); gastrointestinal tumors (3); myelodysplastic syndrome (3); abortion (2); adenocarcinoma (2); benign prostate hyperplasia (2); chronic hepatitis B (2); colorectal carcinoma (2); gastric cancer (2); hepatitis B (2); immune dysfunction (2).
A further 71 diseases each share a sentence with NCR3 in 2 papers or fewer.